AR (androgen receptor)
Diseases named in the same sentence as AR in open-access papers (continued):
Sharing a sentence is not in itself a finding about the gene and the disease.
cancer (continued). "However, cancer cells can become resistant to castration through multiple mechanisms, including androgen receptor amplification or mutation, the production of ligand-independent splice variants, and androgen production by adrenal or cancer cells." (PMID 40805173, 2025). "A genomics study using the TCGA-SKCM data revealed that increased AR signal was significantly associated with exhaustion of CD8+ T cells, and blocking AR signaling could synergize with T cell-based cancer immunotherapy." (PMID 41228208, 2025). "In some cancers, higher AR activity is linked to worse survival, suggesting that therapies targeting AR could help certain patients." (PMID 41228208, 2025). "We provide an overview of novel targeted agents and key insights about new treatment modalities with an emphasis on the androgen receptor signaling pathway, cancer stem cell-associated pathways, phosphatidylinositol 3-kinase (PI3K)/AKT pathway, growth factor signaling, and immunotherapy." (PMID 40003864, 2025). "Further research is needed to determine a possible U-shaped relationship of T with cancer risk, and to decipher the role of testosterone and AR in some of these tumors to facilitate our understanding of sex dimorphism and to explore novel T/AR-based treatment options." (PMID 41228208, 2025). "The clear distinction between basal and luminal cells is lost in the overgrown epithelium, and the stroma alignment to the epithelium is compromised with a degraded BM; the stromal AR is lost accompanied by the cell conversion to cancer-associated fibroblasts (CAFs)." (PMID 39459070, 2024). "According to the preclinical models, increased AR expression may make cancer cells more susceptible to supraphysiologic androgen levels, which could result in DNA damage and cytotoxicity." (PMID 39351434, 2024). "Hence the AR pCPS genes and the nine pCPS genes (all AD) known to cause cancer predisposition through gain-of-function (GoF) variation were considered as separate groups." (PMID 38424437, 2024). "They showed that an androgen receptor-derived stapled peptide, called Rh-2025u, which has been shown to interfere in the complex assembly in cancer-associated fibroblasts and prostate tumor cells, can overcome the shortcomings of current still unsatisfactory therapies." (PMID 39409876, 2024). "Additionally, patients with increased cancer progression and resistance to AR-targeting agents exhibited greater expression of AR and variants such as AR-V7." (PMID 38607014, 2024). "Regarding the AR gene, its applicability as a diagnostic tool for extraprostatic cancer and as a predictor for PCa recurrence might constitute an effective tool for outcome prediction." (PMID 38305916, 2024). "The presence of the estrogen receptor (ER), progesterone receptor (PR), and androgen receptor, which are linked to clinicopathological variables, may affect the prognosis among those with these cancers." (PMID 38523927, 2024). "Similarly, receptor tyrosine kinases, estrogen receptor and androgen receptor have all been implicated in the pathogenesis of both cancer and AD." (PMID 39469929, 2024). "The PPFIA4 protein liprin-α4 is involved in the MAPK signalling pathway which may cause castration-resistant PCa through AR pathway independence, and has been proposed as a potential therapeutic target for several cancer types." (PMID 37749167, 2024). "The downregulation of miR-221 in PCa could activate the TGFβ pathway and is associated with AR overexpression, promoting cancer progression." (PMID 39796656, 2024). "However, this binding activity can be abolished by SPOP mutations in PCa, resulting in AR stabilization and the promotion of cancer cell proliferation and metastasis." (PMID 37847340, 2024). "Finally, future studies should probe and validate the potential use of the GR—possibly coupled with other cancer-associated steroid hormone nuclear receptors, e.g., androgen receptor (AR; NR3C4) —as a prognostic and predictive biomarker in NSCLC." (PMID 37759686, 2023).
cancer (continued). "Besides, inhibition of neddylation-dissociated 1 protein (Cand1), cullin-associated targets and androgen receptor (AR) sensitized cancer cells to CRL inhibition." (PMID 37771770, 2023). "Tumors with high AR expression were reported to be associated with pro-cancer regulatory T cells, and those with low AR expression were associated with anti-cancer immune cells, such as CD4, CD8, gamma delta T cells, and memory B cells in ER-positive breast cancer." (PMID 36721218, 2023). "Most metastatic-enriched cancer drivers had a cancer-type-specific enrichment, including well-established resistance gene drivers associated with anticancer therapies, such as AR and ESR1 alterations in patients with prostate and ER+ breast carcinomas treated with hormone deprivation therapies." (PMID 37165194, 2023). "Indeed, RB1 inactivation has been linked to cancer initiation and progression and resistance to several targeted therapies, including androgen receptor (AR) antagonists, ER antagonists, CDK4/6 inhibitors, and EGFR tyrosine kinase inhibitors." (PMID 36928314, 2023). "Interestingly, it was reported that AR is implicated in the development and progression of various cancer types, including prostate, breast, ovarian, etc.." (PMID 36142861, 2022). "A pathway to oncogenesis in males occurs through involvement of the androgen receptor (AR) signalling pathway, which is common to cancer evolution caused by diverse viruses including HBV, EBV, HTLV-1, HHV8 and HPV78, and is also associated with the evolution of prostate cancer." (PMID 36212217, 2022). "Notably, long-term AR-targeted treatment causes changes in the properties of cancer cells and dedifferentiates them into more aggressive PC with neuroendocrine characteristics (NEPC) that express neural markers (synaptophedin, chromogranin A, NSE, etc.)." (PMID 36263200, 2022). "Here we show that AR can target unknown cancer-related genes and affect their expression, which may be associated indirectly with molecular pathways related to cancer or anti-cancer phenotypes." (PMID 35568821, 2022). "Nevertheless, our results suggest that AR p.H875Y mutation could be a promising biomarker for discriminating healthy subjects from cancer patients, especially CRC, bladder, and prostate." (PMID 35053623, 2022). "With the system we developed in this study, we were able to perform multiple rounds of random AR mutations followed by selection for histidine auxotrophy in the presence of various steroidal compounds mimicking natural evolution of cancer cells under selection pressures by steroid medications." (PMID 36459502, 2022). "In fact, patients with PCa with alterations in canonical WNT pathway genes, which lead to β-catenin activation, are refractory to androgen receptor-targeted therapies, underlying that this genomic alteration may harbor a more aggressive cancer." (PMID 36077746, 2022). "Classical genes associated with an activated status of fibroblasts (FAP, PDGFRβ) were higher in normal adjacent tissues compared with normal tissues from healthy patients whereas AR levels that work as transcriptional repressors of cancer-associated fibroblast activation were lower." (PMID 35740605, 2022). "Given that serum PSA concentration is, in part, dependent on cancer cell AR activity, we assessed whether there was an association between preBAT serum PSA and response to BAT." (PMID 36194476, 2022). "Low expression of AR was associated with a higher risk of cancer brain metastases." (PMID 35886904, 2022). "Thus, this system can be adapted to predict the continuous process of cancer development related to the accumulation of AR mutations in response to medical treatments and other clinically relevant challenges." (PMID 36459502, 2022). "Furthermore, prohibitin (PHB), an AR co-repressor protein, is associated with liver injury and cancer, and importantly in a liver specific PHB knock out mouse model, there was upregulation of genes involved in fibrosis." (PMID 36551674, 2022).
cancer (continued). "Unfortunately, although confirming the ability of AR to antagonize ERα activity, the small sample size used in this study does not allow a relationship between AR and ERα expression in normal mammary epithelium and cancer susceptibility to be established." (PMID 35008851, 2021). "However, in this study, the vesicles with undisclosed cancer-specific surface marker were isolated by immune-capturing and multiple PC-relevant alterations of the androgen receptor were profiled in SEV-associated DNA." (PMID 34572021, 2021). "Diverse sets of cancer hallmarks associated with aberrant functioning of the androgen receptor (AR), which is induced by androgen deprivation therapy (ADT), are the key driving forces behind the uncontrollable growth and metastasis of PCa and its transition into mCRPC." (PMID 33807895, 2021). "Among several putative risk factors involved in the development of PCa, such as mutations in genes associated with DNA repair and androgen receptor (AR) activation, elevated chronic inflammation in the prostatic microenvironment is known to be correlated with cancer development." (PMID 34063828, 2021). "Indeed, the AR is associated with favourable clinicopathological features and a better outcome in this subset of cancers and represents a positive predictive biomarker of the response to endocrine therapy." (PMID 35008851, 2021). "In addition, the nine mRNAs of the ceRNA regulatory networks included GRK4, PCYT2 and RGSL1, which showed prognostic relevance and was associated with cancer-related pathways such as DNA Damage, AR, ER, RASMAPK, and TSC-mTOR." (PMID 34621245, 2021). "Thus, AR loss can have a two-edged sword effects on cancer cells versus surrounding stromal cells, while inducing cellular senescence in both." (PMID 33112375, 2021). "However, patients with BXDC2-negative/AR-positive muscle-invasive tumor had an insignificantly (p = 0.070) or significantly (p = 0.041) higher risk of disease progression or cancer-specific mortality, respectively." (PMID 33652650, 2021). "Finally, to test if the mutations were simply owing to the specific chromosomal locations where AR binds we compared the mutational signatures at ARBS in all cancer types." (PMID 32047165, 2020). "Consistent with other cancer types, an increase in glucose uptake or transporter is also associated with elevated glycolytic activity and emerging evidence has established the significance of the AR in glycolysis." (PMID 32927797, 2020). "22Rv1 cancer cell lines were resistant to hormone therapy at conventional chemotherapy including two new 2nd generation drugs enzalutamide and abiraterone owing to the presence of the androgen receptor splice variant-7 (AR-V7)." (PMID 32867339, 2020). "The frequency of ARBS mutations and importance of AR signaling in PCa cancer progression suggest that these somatic mutations could potentially alter gene transcription." (PMID 32047165, 2020). "To extract information specific to an individual’s cancer, we then focused on an orthogonal methylation signature, which revealed enrichment for androgen receptor binding sequences and hypomethylation of these segments associated with AR copy number gain." (PMID 32149736, 2020). "Moreover, with the phosphorylation on AR caused by Pim1 on serine-213 residue, cancer cells (prostate) have become more aggressive and unaffected by androgen ablation therapy." (PMID 32961987, 2020). "Furthermore, AR binds to different genomic sites in prostate fibroblasts compared to the epithelium and to cancer-associated fibroblasts (CAFs), indicating different roles of AR in epithelial or stroma cellular contexts." (PMID 33334054, 2020). "Finally, AR overexpression (Allred score ≥ 7) was associated with longer cancer-specific survival (HR = 0.46, 95% CI: 0.31–0.69, p = 0.002) by univariate survival analysis." (PMID 31888566, 2019).
cancer (continued). "Importantly, this study showed that 89% of individuals with mCRPC harbor a clinically actionable aberration, including 63% with aberrations in AR, 65% in other cancer-related genes, and 8% with actionable pathogenic germline alterations." (PMID 31366128, 2019). "Having demonstrated that miR-346, -361-3p and -197 modulate AR activity, proliferation and apoptosis in PC, we hypothesised that these miRs may alter other cancer progression-associated processes." (PMID 31043708, 2019). "Despite the clear relationship between poor outcome and loss of stromal AR, the underlying mechanism involving AR signaling in CAFs and consequences in cancer progression and outcome remains largely unknown." (PMID 29808619, 2018). "Considering the significant loss of intracellular zinc and the dominant growth-modulating role of AR during PCa development, loss of zinc may be a critical step in the transformation of normal cells to cancer cells." (PMID 30297600, 2018). "Importantly, this cohort had benign and cancers samples taken from each patient, which showed that the loss of AR was specific to the cancer associated stroma." (PMID 28117763, 2017). "In experiments in which mutated AR cDNA was expressed in cancer or other cell lines, it could be demonstrated that anti-androgens caused a higher transactivation in the presence of mutated AR." (PMID 29214142, 2017). "Moreover, AR overexpression is associated with acquisition of resistance to tamoxifen and aromatase inhibitors, which is key for cancer progression." (PMID 27746764, 2016). "To help establish whether AR signaling affects EC progression, we used cBioPortal to examine cross-cancer alteration summaries of AR, which included AR amplification, mutation, and deletion." (PMID 26397136, 2015). "NCOA2, KDM1A, KDM4A, KDM5B and MED1 are AR coregulators implicated in prostate and other cancers." (PMID 26461474, 2015). "However, after an initial response, the cancer eventually recurs in an incurable, castration-resistant form, as a result of amplification of AR protein, mutations of AR gene, and elevated production of AR variants." (PMID 26074877, 2015). "In addition, ATAD2 was also directly associated with AR to activate AR-mediated transcription and was required to regulate the expression of androgen-induced genes that controlled cancer cell proliferation and survival." (PMID 26697062, 2015). "In addition, we found that restoration of miR137 expression down-regulates expression of VEGFA, an AR target gene, which suggests a role of miR137 loss also in cancer angiogenesis." (PMID 26461474, 2015). "Another important cancer-associated transcription factor that is shared among the modules is AR, a steroid hormone receptor that regulates downstream processes such as proliferation and differentiation and whose mutation has been shown to play important parts in cancer." (PMID 24523864, 2014). "Treatment of castration-resistant PCa (CRPC) is challenging since growth of the cancer at this stage is hypothesized to be regulated by androgens, and mutations of the androgen-receptor (AR) genes are common." (PMID 24137376, 2013). "The AR gene displays a broad spectrum of variability in the mutations landscape across different ethnical backgrounds that might be differently associated with cancer risk." (PMID 41009328, 2025). "We revealed herein that AA elicits distinct anti-proliferative effects on various human cancers (HepG2, Huh-7, LNCaP, DU-145, C4-2B, 22Rv1, MCF-7, MDA-MB-231, MDA-MB-453, and A549) and normal cell lines (Vero and RWPE1), which may be linked to the AR expression status of the cancer cell lines." (PMID 40940976, 2025). "The AR gene also displays a broad spectrum of variability in both polymorphisms and mutations across different ethnical backgrounds that might be differently associated with cancer risk." (PMID 41009328, 2025).
cancer (continued). "It is believed that progression under ADT is because of the ability of cancer cells to overcome a low androgen environment through upregulation of enzymes involved in androgen synthesis, producing androgen and stimulating their own growth, or overexpression of the AR or mutations of the AR gene." (PMID 39081434, 2024). "A next-generation sequencing (NGS) analysis of the cancer genome maps in 182 CC patients was conducted and results showed that AR amplifications, mutations, and deletions in 7% of patients, indicating that AR has an unknown significance in CC." (PMID 35886904, 2022). "On the other hand, there is only one gene encoding for the androgen receptor (AR), which can form different protein isoforms, the full-length AR (AR-FL) and several AR splice variants (referred to AR-Vs) that have been associated to androgen-independent growth in cancer." (PMID 36189206, 2022). "In this context, women with BRCA mutation and low AR expression in primary cancer could benefit from a targeted follow-up, as they are at greater risk of developing BMs, but prospective studies are warranted to establish reliable risk and prognostic factors for OC BMs." (PMID 32759682, 2020). "Furthermore, androgens/AR have been associated to poor prognosis in a plethora of cancer entities." (PMID 32714315, 2020). "Although ablation of ARs in CAFs could attenuate cancer proliferation, the loss of AR signaling activity is also linked to the onset of metastatic phenotypes such as increased stemness, enhanced cell migration and weakening of the extracellular matrix (ECM) structure and integrity." (PMID 30925918, 2019). "Given the ability of the AR-F876L mutant to mediate enzalutamide resistance by causing enzalutamide to function as an agonist, we first determined whether these inhibitor-refractory cancer cells would be vulnerable to protein degradation." (PMID 30271980, 2018). "Thus, it remains to be determined whether RING1B functionally associates with FOXA1 and AR in other cancer types or during embryonic development." (PMID 30139998, 2018). "Importantly, AR mutations are more frequently detected in this type of cancer." (PMID 28036278, 2017). "Collectively, our data suggest that fibroblast AR may play a key role in regulating cell attachment, and in organization of the ECM, and that a loss of stromal AR creates a passive ECM environment that is less adhesive for cancer epithelia and more conducive for metastatic spread." (PMID 25965833, 2015). "Amplification of the gene encoding the androgen receptor (AR), which typically acts as a transcription factor upon binding to androgenic hormones, occurs in approximately 80% of the CRPCa cases, representing the most common genetic alteration in this type of cancer." (PMID 24681825, 2014). "Furthermore, PP may influence several signaling pathways, including UPR, Wnt, and AR, to inhibit cancer cell proliferation, although the underlying molecular mechanisms await further investigation." (PMID 23061049, 2012). "However, on sum the clinical evidence and our theoretical results suggest that low serum testosterone induces selection for AR overexpression, which in turn may predispose cancer to treatment-resistance." (PMID 20406442, 2010). "In this study, we investigated the relationship between AR activity and immune cell signaling across many cancer types." (PMID 41486951, 2026). "This has been shown in the androgen receptor signaling, metabolic pathways and the immune response of the cancer varies between populations 70-75." (PMID 41584049, 2026). "We also observed that AR activity varied not only across cancer types but also among patients within each cancer cohort." (PMID 41486951, 2026). "Its high expression positively correlates with PCa malignancy and promotes cancer cell proliferation in an AR-dependent manner." (PMID 41431399, 2026). "PVT1 is upregulated in several cancer types and has been shown to interact with the androgen receptor in prostate cells." (PMID 41792045, 2026).